MALT1 (MALT1 paracaspase)
Diseases named in the same sentence as MALT1 in open-access papers (continued):
Sharing a sentence is not in itself a finding about the gene and the disease.
colitis (12 papers, 2016 to 2025). Inflammation of the colon. "RNA-seq analysis of human UC colon tissue demonstrated a positive correlation of these wound healing associated and STAT3-regulated genes with MALT1 gene expression levels during active colitis." (PMID 37108564, 2023). "In this study we identified the MALT1 protease as a central regulator of colitis associated mucosal healing." (PMID 37108564, 2023). "Several previous studies disclose that MALT1 leads to T cell activation and differentiation into Th1 and Th17 cells in a series of infection‐associated diseases including colitis and encephalitis." (PMID 35262976, 2022). "Meanwhile, in vivo, the MALT1 deficiency colitis mouse model displayed a reduction of the Th17 cell amount and IL‐17A (Th17 cell secreted cytokines)." (PMID 34273195, 2021). "The mechanisms underlying the inhibitory effects of MALT1 in DSS-induced colitis have been ascribed to the inhibition on NF-κB and NLRP3 inflammasome activation in macrophages, thus implying that MALT1-NF-κB signaling regulates NLRP3 inflammasome activation." (PMID 28179906, 2017). "The underlying mechanisms for the protective effect of MALT1 inhibitors in DSS-induced colitis may be attributed to its inhibition on NF-κB and NLRP3 inflammasome activation in macrophages." (PMID 27105502, 2016). "Here we show that the MALT1 protease inhibits Acsl4 expression during recovery from experimental colitis in mice." (PMID 37108564, 2023). "We demonstrate a significant enrichment of MALT1 gene and protein expression in colonic epithelial cells of UC patients, as well as in the context of experimental colitis." (PMID 37108564, 2023). "Recently, abnormally elevated MALT1 has been studied in a series of infection‐associated diseases such as acquired immune deficiency syndrome (AIDS), virulent rabies, and colitis, whereas its dysregulation in sepsis needs further exploration." (PMID 35262976, 2022). "Overall, our study found that new type inhibitor MI-2 has certain improvement effect on DSS-induced murine colitis by targeting MALT1-NF-κB and NLRP3 signal pathway, which suggests a new strategy for clinical treatment of colitis." (PMID 27105502, 2016). "The scaffold function of MALT1 has been proposed as a therapeutic target in experimental colitis." (PMID 37108564, 2023). "Pharmacological inhibition of the MALT1 protease during recovery from experimental colitis significantly reduced Stat3 expression levels as well as STAT3 activation in the intestinal epithelium, which in turn might have promoted the delay in mucosal healing." (PMID 37108564, 2023). "This further strengthens the hypothesis that in the context of colitis, MALT1 might promote the activation of STAT3." (PMID 37108564, 2023). "The probable reasons might be that: (a) MALT1 was positively correlated with the accumulation of NF‐κB p65, while NF‐κB p65 was overexpressed in colitis mouse models." (PMID 34997981, 2022). "The results of this study show that the MALT1 inhibitor MI-2 mitigated DSS-induced colitis by modulating the host inflammatory response and might be associated with changes in microbiome profile." (PMID 30249750, 2018). "In particular, treatment with two specific MALT1 inhibitors, MI-2 and mepazine, dose-dependently attenuated the symptoms of colitis in mice through a decrease in protein and mRNA levels of colonic TNF, IL-1β, IL-6, IL-18, IL-17A, and IFN-γ pro-inflammatory cytokines." (PMID 28179906, 2017). "To examine whether MALT1 inhibitors could be used for treating colitis, we first examined the effects of known MALT1 inhibitors mapzine and MI-2 in an animal model induced by DSS drinking." (PMID 27105502, 2016). "Our results showed that MALT1 inhibitors could suppress NLRP3 inflammasome activation in DSS-induced colitis model." (PMID 27105502, 2016). "Besides, knocking down MALT1 ameliorates colitis via blocking Th17 and Th1/17 cells activation." (PMID 35967391, 2022).
colitis (continued). "Here, we show that MI-2, a selective inhibitor of mucosa-associated lymphoid tissue lymphoma translocation-1 (MALT1), alleviated excessive inflammatory responses and was associated with restoration of healthy intestinal microbiome in mice suffering from dextran sulfate sodium (DSS)-induced colitis." (PMID 30249750, 2018). "Analysis of a DSS time course RNA-seq dataset further revealed increased expression of Malt1 and the CBM complex protein Card9 during active colitis." (PMID 37108564, 2023). "However, whether MALT1 inhibitors could ameliorate colitis remains unclear." (PMID 27105502, 2016). "Our study here characterized that inhibitors of MALT1, would be safe and potent for the treatment of DSS-induced murine colitis by inhibiting NF-κB and NLRP3 inflammasome activation in macrophage." (PMID 27105502, 2016). "Consistently, MALT1 inhibitors also suppressed Th1 and Th17 differentiation in mice with DSS-induced colitis." (PMID 27105502, 2016). "To study the expression of Malt1 during the onset, progression and resolution of mucosal inflammation, we investigated Malt1 expression in an RNA-seq dataset from a murine experimental dextran sodium sulfate (DSS) colitis time course." (PMID 37108564, 2023). "MALT1 was expressed in the intestinal tissue of control mice and mice with DSS-induced colitis." (PMID 30249750, 2018). "In the present study, we examined the pharmacological effect of two specific MALT1 inhibitors MI-2 and mepazine on the dextran sulfate sodium (DSS)-induced experimental colitis in mice, followed by mechanistic analysis on NF-κB and NLRP3 inflammasome activation." (PMID 27105502, 2016). "To examine the effects of MALT1 inhibitors on the cytokine expression in acute DSS colitis model, we measured the levels of IL-1β, IL-6, TNF, IFN-γ, IL-17A and IL-18 in colons of mice following induction of colitis and treatments with MALT1 inhibitors." (PMID 27105502, 2016).
glioblastoma (12 papers, 2018 to 2025). The most malignant astrocytic tumor (WHO grade IV). "MALT1 plays an important role in cancer, including glioblastoma, by driving tumor progression through both cell-intrinsic and cell-extrinsic mechanisms." (PMID 40338274, 2025). "In glioblastoma stem-like cells, mepazine, another MALT1 inhibitor, and MALT1 siRNA were reported to blunt mTOR activation, as assessed through the phosphorylation of Akt, p70 S6K, and S6 ribosomal protein." (PMID 38097554, 2023). "MALT1 was also recently reported to be aberrantly expressed in solid tumors, including glioblastoma multiforme, especially in PCa." (PMID 34926571, 2021). "Our study explored the roles of lncRNA HOXD-AS2 in glioblastoma cell proliferation, migration and invasion by regulating the miR-3681-5p/MALT1 signaling pathway." (PMID 34802389, 2021). "The relevance of MALT1 as a protooncogene has been recently extended to additional malignancies including melanoma and glioblastoma, in which MALT1 can be overexpressed." (PMID 30214442, 2018). "Furthermore, in glioblastoma, MALT1 regulates the mesenchymal phenotype by modulating NF-κB signaling, and its repression by miR-181d shifts the tumor toward a less malignant proneural subtype." (PMID 41567547, 2025). "HOXD-AS2 could promote glioblastoma cell proliferation, migration and invasion by regulating the miR-3681–5p/MALT1 signaling pathway, TENT4A indirectly regulatesRAD18 via the tumor suppressor CYLD and via PAXIP1-AS2 in endometrial cancer." (PMID 36911393, 2023). "In addition, biperiden produced, mainly, autophagy in glioblastoma cells, which could be explained by blocking MALT1 protease activity, which increases autophagy and culminates in lysosome-mediated cell death and concomitantly with the inactivation of mTOR." (PMID 36447028, 2022). "Moreover, other researchers also found that miR‐181d could attenuate the mesenchymal phenotype by directly repressing MALT1 in glioblastoma." (PMID 32452133, 2020). "Interestingly, MALT1 was identified as a direct target of miR‐181d, which could attenuate the mesenchymal phenotype by directly repressing MALT1 expression in glioblastoma." (PMID 32452133, 2020).
breast carcinoma (11 papers, 2016 to 2025). "Although abnormal MALT1 expression is closely associated with lyphomagenesis and antoimmune diseases, the function of MALT1 in breast cancer is still unclear." (PMID 36797769, 2023). "PAR1 is a thrombin-responsive GPR and its stimulation causes an enhancement in MALT1 protease activity in both osteosarcoma and breast cancer cells, potentially associating with other aggressive phenotypes." (PMID 35347106, 2022). "Accordingly, the number and size of metastatic tumor nodules found in the lungs of nude mice injected with MALT1-deficient MCF7-N55 breast cancer cells are greatly attenuated compared to controls." (PMID 35203553, 2022). "MALT1 expression has been noted in several types of cancer, with low expression levels in breast cancer indexed in the Human Protein Atlas database." (PMID 36797769, 2023). "In our cohorts of breast cancer patients, MALT1 expression was barely present in tumor cells but was enriched in CD68+ TAMs in breast cancer tissues with high expression cSERPINE2." (PMID 36797769, 2023). "Here, we found that MALT1 is barely expressed on tumor cells but is widely expressed on TAMs in breast cancer patients with high expression of cSERPINE2." (PMID 36797769, 2023). "The stabilized MALT1 activates CARMA3–Bcl10–MALT1 pathway in angiotensin II receptor-positive breast cancer, leading to the promotion of cancer cell proliferation and invasion." (PMID 35006464, 2021). "Aberrant CARMA3/BCL10/MALT1 has been indicated in several cancers, including ovarian cancer, breast cancer, and prostate cancer 59-61." (PMID 33052237, 2020). "They demonstrated that tumor exosomal cSERPINE2 from breast cancer could upregulate MALT1 in TAMs, which then activated the NF-κB and increased the secretion of IL-6 by TAMs." (PMID 40443670, 2025). "This “spatially isolated” MALT1 expression and its regulation may contribute to breast cancer immune evasion and promote tumor progression." (PMID 36797769, 2023). "Similarly, in proteinase-activated receptor 1 (PAR1)-driven tumors, both inhibition and silencing of MALT1 impairs the expression of NF-κB target genes, such as IL1B, CXCL8, and MMP9, each associated with the manifestation of malignant features in breast cancer and osteosarcoma (OS)." (PMID 35203553, 2022). "Indeed, we found that that AGTR1 overexpression, in both breast cancer patient samples and breast cancer cell lines, drives NF-κB activation and an associated NF-κB gene expression signature; as we expected, CARMA3, Bcl10, and MALT1 are each required for this to occur." (PMID 30158935, 2018). "Collectively, these results suggest that the MALT1 levels are regulated by tumor exosomal cSERPINE2 by sponging miR-513a-5p in TAMs, while this regulatory mechanism of MALT1 is not present in breast cancer cells." (PMID 36797769, 2023). "Recent studies found that MALT1 is required to activate the NF-κB signaling and promote cancer progression in the non-lymphoid system, such as breast cancer, lung cancer, melanoma, and cholangiocarcinoma." (PMID 33802402, 2021). "To determine whether MALAT1 expression in breast cancer is capable of exerting prognostically significant effects, we compared DSS (disease-specific survival) between patients grouped according to high or low MALT1 expression." (PMID 27250026, 2016).
lung carcinoma (11 papers, 2012 to 2022). "The authors have demonstrated that the silencing of either CARD10 or MALT1 in EGFR-overexpressing lung cancer cells correlates with reduced NF-κB activity, cancer cell proliferation, migration, survival, and tumor burden in vivo." (PMID 35203553, 2022). "In the lung cancer cell line A549, MALT1 cleaves the C10BM complex member CARD10 after the arginine residue at position 587, thereby dampening its capacity to activate NF-κB." (PMID 35203553, 2022). "A 2016 study showed that MALT1 (mucosa-associated lymphoid tissue 1) is involved in EGFR-induced NF-κB activation in lung cancer cells, and that MALT1 inhibition impaired EGFR-dependent NF-κB activation." (PMID 34206026, 2021). "Previous studies indicated that MALT1 was required for the EGFR- and TNF-α/NF-κB signaling-induced IL-6 production in lung cancer progression." (PMID 33802402, 2021). "The protein forms a complex with MALT1, which in turn has recently shown to be required for EGFR-induced NF-κB activation and to contribute to EGFR-driven lung cancer progression." (PMID 27279498, 2016).
melanoma (11 papers, 2017 to 2024). A malignant, usually aggressive tumor composed of atypical, neoplastic melanocytes. "Exogenous expression of the active MKK7 is sufficient to restore melanoma growth and migration in cells with MALT1 loss." (PMID 28759024, 2017). "Indeed, MALT1 is highly expressed in a subset of melanoma associated with poor prognosis." (PMID 30214442, 2018). "Additionally, exogenous induction of NF-κB prevents melanoma cell death sensitized by MALT1 loss." (PMID 28759024, 2017). "Since the increased IFNγ production during incomplete C11BM inhibition provokes PD-L1 expression in the melanoma cells, the combination of MALT1 inhibitors and anti-PD1 immune checkpoint therapy exhibits synergistic effects in the inhibition of tumor growth." (PMID 35203553, 2022). "In melanoma, the MALT1, MKK4/7, and JNK/AP1 signaling cascade promotes melanoma cell proliferation and migration, whereas CYLD inhibits it." (PMID 32252279, 2020). "Next, we established a melanoma model in wild-type mice and pharmacologically blocked MALT1 paracaspase activity in these animals in vivo." (PMID 31138793, 2019). "In line with our cell type-specific genetic analysis, it is likely that much of the beneficial consequences of MALT1 inhibitors in the tested melanoma model are mediated via inhibitory effects on Tregs." (PMID 31138793, 2019). "MALT1 gene silencing sensitized melanoma cells to death induction by TRAIL, and induction of p65ER with 4-OHT prevented it." (PMID 28759024, 2017). "Most importantly, gene silencing of MALT1 markedly reduces subcutaneous melanoma growth and pulmonary metastasis." (PMID 28759024, 2017). "In agreement with protein upregulation, MALT1 mRNA was increased in metastatic melanomas, as shown in two independent gene expression profile data sets." (PMID 28759024, 2017). "MALT1 inhibition via shRNA-mediated gene silencing or pharmacologically with MI-2 compound markedly reduced cell growth and migration of A2058 and A375 melanoma cell lines in vitro." (PMID 28759024, 2017). "Gene silencing of MALT1 markedly slowed melanoma growth in vitro and in vivo, which was correlated with reduced JNK and NF-κB pathway activation." (PMID 28759024, 2017). "To establish a clinical relevance of MALT1 to melanoma, we first examined the expression status of MALT1 in melanoma cells." (PMID 28759024, 2017). "Here, we demonstrate that MALT1 is overexpressed in malignant melanoma cells, and predicts a poor disease-free survival." (PMID 28759024, 2017). "JNK/c-Jun also mediates melanoma cell proliferation and motility driven by MALT1." (PMID 32252279, 2020). "In this study, we sought to examine the role of MALT1 in melanoma." (PMID 28759024, 2017). "To test whether MALT1 is required for NF-κB activation in melanoma cells, we treated A2058 and A375 cells with 50 ng/ml tumor necrosis factor-α (TNFα) for 15 min." (PMID 28759024, 2017). "To examine whether MALT1 is important for melanoma growth in vivo, we injected A2058 and A375 cells subcutaneously into immunodeficient NSG mice." (PMID 28759024, 2017). "Future studies may be directed to characterizing the full-spectrum of MALT1 upstream and downstream regulators in melanoma to determine whether MALT1 exhibits any functional dichotomy." (PMID 28759024, 2017). "Together, current findings underscore MALT1 as a promising therapeutic target for melanoma." (PMID 28759024, 2017). "Genetic and pharmacological inhibition of MALT1 inhibits melanoma growth and motility." (PMID 28759024, 2017). "Furthermore, MALT1 gene silencing inhibits cell growth of melanoma in vitro and in vivo." (PMID 33802402, 2021). "To determine whether MALT1 plays an important role in melanoma growth, we first performed shRNA-mediated gene silencing of MALT1 (shMALT1) in metastatic human melanoma A2058 and A375 cell lines through lentiviral gene transduction with two different shRNA constructs." (PMID 28759024, 2017).
melanoma (continued). "Next, we asked whether JNK/AP1 signaling is crucial for MALT1-mediated melanoma cell growth." (PMID 28759024, 2017). "In malignant melanoma (MM) and cholangiocarcinoma (CCA), MALT1 has been reported to be overexpressed and thus to contribute to survival and metastasis." (PMID 35203553, 2022). "The interaction among CARMA1, BCL10, and MALT1 also affects the activity of downstream NK-KB signaling pathway, and the control of BCL10 on MALT1 paracaspase activity affects the formation of malignant melanoma TME." (PMID 35927985, 2022). "In malignant melanoma models, acute genetic blockade of BCL10 signaling selectively in Tregs or pharmacological MALT1 inhibition enhances anti-tumor immune responses." (PMID 31138793, 2019). "Together, these findings demonstrate that MALT1 promotes melanoma cell proliferation and motility through JNK/c-Jun, and enhances melanoma cell survival through NF-κB, underscoring MALT1 as a potential therapeutic target and biomarker for malignant melanoma." (PMID 28759024, 2017). "Our findings demonstrate that MALT1 promotes melanoma progression and survival through JNK/c-Jun and NF-κB signaling pathways, underscoring MALT1 as a potential therapeutic target for melanoma." (PMID 28759024, 2017). "Yet, the role of MALT1 in other solid cancers such as melanoma is not well-understood." (PMID 28759024, 2017). "However, in the context of melanoma, MALT1 knockdown also suppresses activation of the JNK/AP-1 signaling pathway, indicating that the cellular effects observed upon MALT1 protease inhibition might not be attributable solely to the specific downregulation of NF-κB." (PMID 35203553, 2022).
rheumatoid arthritis (9 papers, 2014 to 2025). A chronic, systemic autoimmune disorder characterized by inflammation in the synovial membranes and articular surfaces. "MALT1 regulates immunity and inflammation in multiple ways, while its role in rheumatoid arthritis (RA) is obscure." (PMID 35967391, 2022). "A recent report suggested inhibition of osteoclastogenesis and protection in a model of rheumatoid arthritis by the structurally unrelated MALT1 active site inhibitor MI-2." (PMID 30513612, 2018). "Emerging evidence suggests that mucosa-associated lymphoid tissue lymphoma translocation 1 (MALT1) is a key regulator of inflammatory diseases; however, the pathological role of MALT1 in rheumatoid arthritis (RA) is not well understood." (PMID 28928392, 2017). "MALT1 has recently been suggested as a therapeutic target in rheumatoid arthritis." (PMID 30513612, 2018).